INS (insulin)
Diseases named in the same sentence as INS in open-access papers (continued):
Sharing a sentence is not in itself a finding about the gene and the disease.
diabetes (continued). "Previous studies have shown that this is due to changes in insulin signalling that induces a diabetes-like phenotype in these individuals." (PMID 40845064, 2025). "Researchers have looked into CRISPR to increase insulin sensitivity and restore pancreatic β-cell function in diabetes." (PMID 40430848, 2025). "Participants included people with diabetes who use insulin, caregivers and primary and secondary care healthcare professionals." (PMID 40324886, 2025). "Insulin is well known to stimulate intracellular potassium shifts, and a case–control study in patients with diabetes suggested a dose-dependent relationship between insulin use and incident psoriasis." (PMID 40606452, 2025). "Diabetes mellitus was more prevalent in Q5 for oral medication/dietary control (29.5% vs. 27.9%, p < 0.001) and insulin therapy (8.7% vs. 9.4%, p < 0.001)." (PMID 40390998, 2025). "Type 2 Diabetes Mellitus (T2DM) is a chronic metabolic disorder characterized by inadequate insulin production and, consequently, hyperglycemia." (PMID 40429939, 2025). "Follow-up studies are needed to validate the in vivo efficacy of BSP in animal models of diabetes and to elucidate their effects on glucose transport, insulin signaling pathways, and intestinal flora." (PMID 40428614, 2025). "Type 2 diabetes mellitus (T2DM) develops because of resistance to insulin, which is prevalent because of the consumption of high-calorie food and lack of physical exercise." (PMID 40438603, 2025). "Despite the fact that using an insulin pump is widely known to have benefits on diabetes management in adolescents, in Palestine, insulin pumps are not covered by insurance and are very expensive to buy and maintain." (PMID 40303937, 2025). "The cost and related insurance coverage of diabetes medications, particularly insulin, represents a major contributor to financial toxicity." (PMID 40358737, 2025). "Schools and PWD should be instructed to contact the diabetes team to confirm doses in case the insulin delivery modality is changed." (PMID 41230085, 2025). "Evidence indicates that celastrol regulates insulin signaling through multiple mechanisms, alleviating insulin resistance and demonstrating therapeutic potential for diabetes management." (PMID 40897829, 2025). "These breakthroughs are intended to revolutionize the treatment of diabetes by providing a non-invasive alternative to injecting insulin, thus improving patient adherence and quality of life." (PMID 41586190, 2025). "For individuals with diabetes, homelessness imposes practical and psychosocial barriers: safe storage of insulin, regular meals, stigma, mobility between services and attendance at follow-up without a fixed address." (PMID 41158567, 2025). "T3DM specifically refers to the brain’s neurons becoming unresponsive to insulin, underscoring the strong link between diabetes and AD." (PMID 39966707, 2025). "Glucose-sensitive MNs containing phenylboronic acid provided self-regulated insulin release, mimicking the function of pancreatic cells for more effective diabetes treatment." (PMID 40136911, 2025). "Circular diagram illustrating treatments for Type 1 Diabetes Mellitus, segmented into insulin weekly formulation, blood glucose monitoring technology, gene editing, immune regulation, and other therapies like stem cell, curcumin, and probiotics." (PMID 41142642, 2025). "OSA contributes to diabetes through intermittent hypoxia, increased sympathetic activity, and elevated inflammation, which impair glucose homeostasis and insulin sensitivity." (PMID 40341843, 2025). "This highlights the significant impact of insulin dysregulation on bone health and the significance of osteoporosis as a comorbidity in individuals with diabetes." (PMID 40564223, 2025). "The use of ESYSTA improved HbA1c levels and other secondary outcomes in people with diabetes who are treated with insulin in comparison with German SoC in the context of DMP." (PMID 40661654, 2025).
diabetes (continued). "There was a trend toward increasing age, longer diabetes duration, worse glycemic control despite greater insulin use, and greater macrovascular disease burden across the groups." (PMID 40303548, 2025). "Approximately 18% of patients from our database suffered from either insulin-dependent or non-insulin-dependent diabetes mellitus, which is comparable to the results of other studies." (PMID 40283383, 2025). "The main limitation of this study is the inability to exclude other diabetes subtypes that necessitate early insulin prescription." (PMID 40897507, 2025). "In parallel, the rapid spread of diabetes technologies—such as continuous glucose monitoring and insulin pumps—calls for PROMs that can capture patients’ digital and technology-related experiences, an aspect still largely unexplored." (PMID 41302228, 2025). "Several decades ago, he developed a classification of diabetes mellitus, in which he combined the concepts of insulin-dependent and insulin-independent diabetes mellitus (diabetes mellitus types 1 and 2 in modern classification)”." (PMID 41269205, 2025). "Many participants mentioned that it would be helpful if HCPs strive to increase awareness, position diabetes care within obesity management, and aim to reduce their insulin needs." (PMID 41497311, 2025). "The expression levels of MOTS-c are negatively correlated with body mass index (BMI), fasting insulin, and glycated hemoglobin levels, suggesting its potential role in diabetes management." (PMID 40264667, 2025). "Advances in diabetes management, including subcutaneous insulin infusion systems, and continuous glucose monitoring technologies, have significantly improved both survival and quality of life in T1D individuals." (PMID 41148826, 2025). "It significantly enhances the precision of insulin delivery while reducing the minimum infusion dosage of the insulin pump, thereby offering a more finely tailored treatment approach for diabetes patients." (PMID 40465596, 2025). "Harmal-e-shami has been extensively investigated for its potential role in diabetes management, with studies yielding variable outcomes regarding its effects on glucose homeostasis and insulin regulation in animal models." (PMID 41007291, 2025). "In several studies, insulin-treated mothers diagnosed with MODY-monogenic diabetes delivered earlier than their diet-managed counterparts." (PMID 40649834, 2025). "In contrast, R6C and C43G nearly abolish insulin production, correlating with earlier and more severe diabetes." (PMID 40869431, 2025). "In diabetes, insulin resistance and metabolic dysfunction hinder the body’s ability to respond effectively to insulin, resulting in hyperglycemia and a myriad of clinical complications, including delayed wound healing." (PMID 40280905, 2025). "Studies suggest that IQGAP1 plays a vital role in regulating metabolic homeostasis, fat cell function, and insulin sensitivity, with potential implications for diseases like obesity and diabetes." (PMID 41035668, 2025). "Insulin is used in the treatment of type 1 diabetes mellitus and late-stage type 2 diabetes mellitus." (PMID 41155876, 2025). "Diabetes mellitus (DM) is a chronic condition characterized by elevated blood glucose levels due to insufficient production or utilization of insulin in the body." (PMID 40791804, 2025). "In diabetes management, glucose-responsive HMNs undergo rigorous testing to confirm their ability to release insulin in response to fluctuating blood glucose levels." (PMID 40136911, 2025). "Regarding the priming of the insulin pens, most of the participants trained by the diabetes educators (54%) were priming the device by observing the drop of insulin at the needle tip." (PMID 40376558, 2025). "Insulin pumps have been used in the management of diabetes since the 1970s, when they were mainly exclusive to those from higher socioeconomic backgrounds." (PMID 40718276, 2025).
diabetes (continued). "Diabetes mellitus is a chronic disease that occurs when the pancreas cannot produce enough insulin or the body cannot use insulin effectively." (PMID 40552040, 2025). "Diabetes mellitus (DM) is a metabolic disorder characterized by hyperglycemia arising from inadequate insulin secretion and/or compromised insulin efficacy." (PMID 40432897, 2025). "Obesity leads to insulin resistance, where the body becomes less responsive to insulin, resulting in elevated blood glucose levels, which is a primary mechanism for the development of diabetes." (PMID 40556851, 2025). "Diabetes is a long-term chronic condition brought on by either inadequate pancreatic synthesis of insulin or inappropriate use of the stored insulin." (PMID 40558679, 2025). "Diabetes is a condition characterized by either inadequate insulin production or insulin resistance, resulting in the accumulation of glucose in the bloodstream, potentially causing significant harm to essential organs." (PMID 39776855, 2025). "Type 1 diabetes mellitus (T1DM) is a chronic disease that destroys insulin-producing β-cells in the pancreas." (PMID 41216603, 2025). "This study evaluated patient-level outcomes of a pilot peer support intervention using DSCs for underserved adults with insulin-requiring diabetes." (PMID 40678170, 2025). "C-peptide is a biomarker for diabetes mellitus management and offers insights into endogenous insulin production." (PMID 40002353, 2025). "Cramer’s V and Cohen d test outcomes reflected a small effect for gender, BMI, insulin treatment, diabetes type, year of diagnosis, and comorbidities." (PMID 40209214, 2025). "The cost of insulin and glucose monitoring devices has emerged as one of the most pressing barriers, with families reporting that they spend 30–50% of their income on diabetes care." (PMID 40938912, 2025). "Alzheimer’s disease (AD) and type 2 diabetes mellitus (DM), both of which are characterized by increased prevalence with aging, have considerable overlap in their risk factors, comorbidities and pathophysiological mechanisms including insulin resistance." (PMID 41446639, 2025). "Insulin resistance (IR) is a core pathological feature of type 2 diabetes mellitus (T2DM) and is closely associated with mitochondrial dysfunction in insulin-sensitive tissues, including skeletal muscle, liver, and adipose tissue." (PMID 41480360, 2025). "GRHs are especially promising for diabetes management, offering a pathway to self-regulated insulin delivery, mimicking pancreatic beta cells, offering glucose-triggered, feedback-regulated insulin release." (PMID 40808075, 2025). "Overall, the antioxidant, anti-inflammatory, and insulin-mimicking properties of chlorophyll derivatives suggest a multifaceted approach to diabetes management." (PMID 40871679, 2025). "Diabetes is characterized by persistent hyperglycemia, insulin dysfunction, and abnormal lipid metabolism that leads to diabetes complications." (PMID 39877627, 2025). "MASH progressing to cirrhosis often coexists with type 2 diabetes mellitus (T2DM), a condition that exacerbates systemic inflammation, insulin resistance, and fibrogenesis—factors implicated in both hepatic and muscular deterioration." (PMID 41464593, 2025). "Myocardial dysfunction and affected electrophysiological properties in diabetes contribute mainly due to metabolic disturbances including hyperglycemia, lipotoxicity and insulin resistance." (PMID 40080468, 2025). "Despite significant advances in insulin therapies and glucose monitoring technologies, pediatric diabetes management continues to pose substantial clinical challenges for families and healthcare providers alike." (PMID 40895926, 2025). "Increasing IDE activity can significantly enhance insulin sensitivity in diabetes while simultaneously facilitating the removal of Aβ in AD." (PMID 40724942, 2025).
diabetes (continued). "Users also highlighted how collecting data from these devices allowed them to make informed decisions about their insulin levels and diabetes management." (PMID 40424579, 2025). "The statistical process control P Chart shows centerline shifts among patients with T1D who were seen for follow-up visits on insulin pump therapy within that month, with a diabetes duration of less than or equal to 1 year." (PMID 40110444, 2025). "Compared to traditional diabetes management strategies, such as manual insulin dosing guided by fixed algorithms or carbohydrate counting, PRIMO-FRL offers a more adaptive and personalized approach." (PMID 40614090, 2025). "Basal rate (BR) adjustment is crucial for managing type 1 diabetes mellitus, accounting for 30% to 50% of total daily insulin needs." (PMID 41313183, 2025). "Glycohemoglobin, glucose, fasting glucose, age, cholesterol, osmolality, BMI, blood urea nitrogen, and insulin exert the greatest influence on diabetes diagnosis." (PMID 40313792, 2025). "GLP‐1RAs have a variety of actions, including those that affect inflammation and insulin sensitivity, which makes them useful tools for managing diabetes and preventing eye disorders." (PMID 40509955, 2025). "The objective of the present study is to determine the prevalence of ACD among children/adolescents with T1D who use glucose sensors and/or insulin infusion sets for diabetes management in the UAE." (PMID 41200730, 2025). "The advancement of diabetes technology, such as automated Insulin Pumps (IP) or CGM, means people with diabetes have more tools available to them with greater capability to help relieve some of the burden of managing their condition." (PMID 41018723, 2025). "Diabetes mellitus (DM) is a metabolic disorder characterized by chronic hyperglycemia resulting from impaired insulin secretion, defective insulin action, or both." (PMID 40943666, 2025). "This education includes understanding diabetes, blood glucose monitoring, insulin administration, nutrition and diet, physical activity, prevention of complications, psychosocial support, and self-management skills." (PMID 40006246, 2025). "The therapeutic efficacy of gene supplementation delivering endocrine proteins, such as growth factors and insulin, has been studied in animal models of obesity and diabetes." (PMID 39949979, 2025). "The inclusion of all stakeholders in insulin therapy, particularly the diabetes education specialists, is essential." (PMID 40376558, 2025). "Nanotechnology enables a comprehensive and interconnected approach to diabetes management, combining real-time biosensing, smart insulin delivery, regenerative tissue engineering, and AI-guided decision systems." (PMID 40574088, 2025). "The themes generated from the data provide useful insights to help inform strategies to enhance insulin safety, staff education, patient empowerment and care experience for older adults with diabetes." (PMID 41358572, 2025). "Some PwT2D struggled to accept their new identity as someone with diabetes or the need to inject insulin, and were significantly affected by the social stigma they experienced." (PMID 40171977, 2025). "Diabetes mellitus is a chronic endocrine disease of relative insulin insufficiency that generally requires daily insulin injections for clinical management, although there is now an oral solution available for newly diagnosed cats." (PMID 41446015, 2025). "The greatest educational needs included information about the illness, the function of the pancreas and insulin effects, relevant diabetes handling, the role of physical activity, the treatment of complications and advances in diabetes treatment." (PMID 41040854, 2025). "In 2022, the American Diabetes Association expanded its recommendations for CGM use for people with any form of diabetes and a variety of insulin regimens." (PMID 40560023, 2025). "The management of type 1 diabetes mellitus involves lifelong insulin therapy to regulate blood glucose levels." (PMID 40002353, 2025).
diabetes (continued). "The DIAMOND trial (clinicaltrials.gov Identifier: NCT02282397), involving participants with diabetes aged >60 years who were using multiple daily insulin injections, assigned participants to either CGM or SMBG." (PMID 41141022, 2025). "These fatty acids interfere with insulin action, leading to insulin resistance, which, if persistent, is likely to develop into diabetes." (PMID 41040857, 2025). "Diabetes Mellitus (type 1 or type 2) is characterised by high blood sugar (hyperglycaemia) due to defective insulin regulation." (PMID 40863620, 2025). "Recently, NF-κB was evaluated in the liver of dogs with experimentally induced type 1 diabetes mellitus, showing a reduction in its activity and in serum liver enzymes in dogs treated with N-acetyl-cysteine and insulin compared to untreated dogs." (PMID 40266905, 2025). "When using an insulin pump, what shouldsomeone with diabetes do FIRST when ketones and blood sugar areabove 300 mg/dL in the morning?" (PMID 40893024, 2025). "In terms of current treatment for diabetes, the majority were on oral hypoglycemics only (179/292, 61.3%), followed by a combination of oral hypoglycemics and insulin (92/292, 31.5%)." (PMID 41183221, 2025). "The patient's pre‐pregnancy insulin requirement was 42 units/day, and her family history included type 2 diabetes mellitus in both maternal grandparents as well as ovarian cancer in her mother." (PMID 41321883, 2025). "Current therapeutic strategies for diabetes management primarily involve oral hypoglycemic agents and insulin therapy." (PMID 41487501, 2025). "Monitoring blood glucose and insulin levels at the normal state or after diabetes induction are easily accessible readouts." (PMID 40869378, 2025). "A recent study demonstrated that ISL can restore metabolic homeostasis in diabetes mice fed a high-fat, high-glucose diet; this effect included improved insulin signaling sensitivity, promotion of liver glycogenesis, and inhibition of liver adipogenesis." (PMID 40365313, 2025). "Amyloid aggregation and insulin ball formation under the skin has also been observed in diabetes patients who regularly take insulin injections." (PMID 40723866, 2025). "This antioxidative activity is believed to enhance the plant’s ability to improve insulin sensitivity, a crucial factor in the management of diabetes." (PMID 40686811, 2025). "In diabetes, disrupted cAMP signaling leads to impaired insulin secretion and excessive glucagon release." (PMID 40822953, 2025). "The discovery of insulin and its role in the development of diabetes mellitus stands as a landmark achievement in 20th‐century medicine, awarding Frederick Banting and James Richard MacLeod the Nobel Prize in Physiology or Medicine in 1923." (PMID 38877295, 2025). "The use of insulin pumps for insulin infusion in vitro is one of the most important methods for the treatment of diabetes." (PMID 40465596, 2025). "Age, sex, diabetes duration, hypertension history, insulin therapy, antihypertensive drugs, HbA1c, eGFR, lipid-lowering drugs, SBP, TBF, SAT, and VAT, PRAT." (PMID 41393943, 2025). "The notable finding from our study is that increased engagement with CGM for people with diabetes on insulin therapy can be more impactful than more‐frequent daily insulin bolus dosing." (PMID 41039947, 2025). "miR-138-5p has been reported to decrease insulin secretion, with obesity-induced adipocytes promoting diabetes through exosomal miR-138-5p-mediated regulation of β-cell function." (PMID 41295241, 2025). "Needle‐free insulin injection has become a recommended method for insulin administration in the Guidelines for the Management of Diabetes Mellitus in the Elderly in China (2024 Edition)." (PMID 41180388, 2025). "The other features consistent with lipodystrophy are leanness with young-onset diabetes (<35 years of age), any syndromic diabetes with very high insulin (>2 units/kg/day) requirement, and diabetes with hepatic steatosis/transaminitis." (PMID 40718185, 2025).